CCL28 (C-C motif chemokine ligand 28)
Diseases named in the same sentence as CCL28 in open-access papers (continued):
Sharing a sentence is not in itself a finding about the gene and the disease.
cancer (53 papers, 2016 to 2025). A tumor composed of atypical neoplastic, often pleomorphic cells that invade other tissues. "CCL28, a chemokine implicated in various cancers, exhibits diverse prognostic impacts depending on the cancer subtype." (PMID 40508156, 2025). "For instance, owing to the positive correlation in PTA, the cancer-associated increase of the chemokine CCL28 abundance increased the abundance of the linked adenylate cyclase ADCY3 that regulates numerous pathways, including calcium signaling." (PMID 33302383, 2020). "An increase in CCL28/MEC expression participates in the development of cancer, causing migration and invasion of hepatocellular carcinoma cancer cells." (PMID 32781743, 2020). "Consistent with its tumorigenic functions, CCL28 expression levels from the Human Protein Atlas are negatively correlated with survival rate in two of the three leading causes of cancer death in the United States, including pancreatic ductal adenocarcinoma (PDAC) and lung cancer." (PMID 36841432, 2023). "Among the upregulated genes were those linked to cancer formation (e.g., STOX1, PEG3, XIAP) and immune cell recruitment (e.g., CCL28, VIM), suggesting a shift towards increased cellular proliferation and remodelling of the immune microenvironment." (PMID 40683913, 2025). "There are a few chemokines that are positively correlated with ASPP1 in cancers, such as CCL28, CX3CL1, CXCL14, and CXCL17." (PMID 39830645, 2024). "Chemokines, such as CCL28, CXCL8, and CXCL16, and chemokine receptors, including CCR1, CCR8, and CXCR2, were positively linked to DLAT expression in various cancers." (PMID 37199628, 2023). "Despite serving as an essential component of the immune system, CCL28 plays a pro-tumoral role in several cancers." (PMID 36841432, 2023). "Activated CCL28 binds to CCR3 and CCR10, and can control the targeted migration of TILs, Tregs, and cancer‐associated stellate cells." (PMID 36952458, 2023). "Some chemokine receptors, such as cCCL27 (8 cancers), CCL28 (7 cancers), CCL16 (5 cancers), CCL17 (5 cancers), and CCL15 (four cancers), were negatively associated with pyroptosis in several cancers." (PMID 35246158, 2022). "The results showed that levels of most of the immunosuppressive cytokines, such as Arg2, CCL28, DNMT1, and EZH2, were upregulated in the high-risk subtype, suggesting that high-risk A-HCC patients have reduced cancer-immunity cycle activity." (PMID 34512165, 2021). "Overall, CCR10–CCL27/CCL28 interactions facilitate Th22 cell migration and activation, contributing to inflammation and positioning this axis as a potential therapeutic target in cancer and other inflammatory diseases." (PMID 41050670, 2025). "Besides, six factors had inverse causal associations with cancer, including CCL15, CCL18, CCL19, CCL20, CCL21, and CCL28." (PMID 38075694, 2023). "Hypoxia upregulates the infiltration levels of Treg cells by increasing the expression of the FOXP3 transcription factor, TGF-β, and CCL28, which may inhibit the anti-cancer immune responses." (PMID 34484235, 2021). "In addition, hypoxia-induced expression of chemokine (C-C motif) ligand-28 (CCL-28) by cancer cells recruits Treg29." (PMID 29371595, 2018). "For this reason, it may increase the sensitivity of cancer cells to CCL28/MEC and CCL27/ESkine." (PMID 32781743, 2020). "The heatmap displayed that GPX4 expression was highly correlated with the levels of numerous chemokines and chemokine receptors, such as CXCL16, CCL28, CX3CL1, CCL5, CCR10, CXCR5, and CXCR3, across the majority of cancer types." (PMID 41142608, 2025). "For the second type of change, miR-125b-high altruistic cancer cells can secrete higher levels of diffusible proteins (IGFBP2 and CCL28) that not only confer benefits but also discourage neighboring cells from turning into altruistic cells." (PMID 39774289, 2025). "Overall, our results implicate the trophic factors CCL28 and IGFBP2 in mediating the fitness benefits conferred by the miR-125bHigh altruistic cancer cells." (PMID 38093346, 2023).
cancer (continued). "For other chemokines, CXCL11 was positively related to approximately all other chemokines except CCL14, CCL15, CCL16, CCL27, CCL28, CXCL6, and CXCL17 in almost all types of cancers." (PMID 35935945, 2022). "Evidence has indicated that Treg cells are recruited to TME through chemokines produced by cancer cells and, in particular, HCC cells have been found to secrete CCL5 and CCL28 chemokines to mediate accumulation of Treg cells." (PMID 35003260, 2021). "Due to the production of CCL28 and CCL27 in the skin, the expression of CCR10 on a cancer cell increases the probability of skin metastasis." (PMID 33076281, 2020). "To investigate the mechanisms that altered migration and invasion of gastric cells, we evaluated the expression of cytokines CCL20, CCL28, and CXCL-2, which promote the migration and invasion of various cancer cells." (PMID 33194715, 2020). "In vitro experiments also show that CCL28 reduces migration and EMT in oral squamous cell carcinoma, but the effect on migration varies among other types of cancer." (PMID 33076281, 2020). "Importantly, the BF BSH-accelerated CRC progression was ameliorated by anti-CCL28 or anti-CD25 antibody treatment, which mainly resulted from enhanced cancer cell apoptosis." (PMID 36765047, 2023). "CCL28 and CCL27 stimulate proliferation and have anti-apoptotic effects on cancer cells." (PMID 33076281, 2020). "Similarly, the interaction between CCL28/CCR10 is described as responsible for the remodeling of lymphatic vessels, increasing the metastatic potential of cancer cells." (PMID 33066172, 2020). "However, the percentage of T cells was reduced in the CCL28 up-regulated LLC, indicating that CCL28 might play different roles in different cancer types." (PMID 39075504, 2024). "However, the molecular and biochemical signaling pathways by which CSC-DC vaccination induces down-regulation of CCR10 on cancer cells, particularly on cancer stem cells, and down-regulation of CCL27 and CCL28 in metastatic target organs have yet to be identified." (PMID 29423335, 2017). "While a consistent negative correlation with a single gene across most cancers was rare, it was a defining feature for a few chemokines, most notably CXCL17 and CCL28." (PMID 41614761, 2025). "Several genes were also, however, inconsistent with the mouse model data including CCL5, CCL20, CCL22, CCL28, CXCL10, and PDL2, suggesting that these features may not be as robustly tissue-specific across different primary cancers." (PMID 33985562, 2021).
infection (13 papers, 2007 to 2025). The state of being infected such as from the introduction of a foreign agent such as serum, vaccine, antigenic substance or organism. "Here, we investigate the function and underlying mechanism of CCL28 during the mucosal response to infection." (PMID 39193987, 2024). "At day 4 post-infection (4 dpi) with STm, we observed a ~fourfold increase of CCL28 by enzyme-linked immunosorbent assay (ELISA) analysis of feces from wild-type mice relative to uninfected controls." (PMID 39193987, 2024). "The functional consequences of CCL28 deficiency varied between the two infections: Ccl28−/− mice were highly susceptible to Salmonella gut infection but highly resistant to otherwise lethal Acinetobacter lung infection." (PMID 39193987, 2024). "In addition, abnormal neutrophil recruitment and activation resulted in increased susceptibility to infection in the gut by Salmonella in CCL28 knockout mice." (PMID 36713846, 2023). "Overall, this study demonstrates that CCL28 plays an important role in the mucosal response to pathogens by promoting neutrophil accumulation at the site of infection." (PMID 39193987, 2024). "Concurrent neutrophil counts in the blood and bone marrow were similar between infected Ccl28−/− mice and wild-type mice, indicating a defect in the accumulation of neutrophils at the mucosal site of infection and excluding a defect in granulopoiesis." (PMID 39193987, 2024). "In a prior preliminary study, we found that Ccl28−/− mice infected with STm exhibited increased lethality compared to their wild-type littermates beginning at day 1 post-infection." (PMID 39193987, 2024). "Following intratracheal Ab infection, we observed a striking phenotype: 75% of wild-type mice died within 48 hr, whereas 88% of Ccl28−/− knockout mice survived through 10 dpi." (PMID 39193987, 2024). "To further elucidate the impact of CCL28 on STm infection dynamics and host responses earlier in the course of infection (2–3 dpi), we examined STm colony-forming units (CFU) in the gastrointestinal contents and extraintestinal tissues." (PMID 39193987, 2024). "CCL28 contributed to neutrophil recruitment during STm gut infection, so we analyzed neutrophil recruitment to the lung mucosa 1 day after Ab infection in wild-type and Ccl28−/− mice." (PMID 39193987, 2024). "Although substantial lung inflammation was observed in both wild-type and Ccl28−/− mice post-infection, immunofluorescence analysis revealed fewer neutrophils (Ly6G+ cells) in the lungs of Ccl28−/− mice." (PMID 39193987, 2024). "Consistent with our initial observation that Ccl28−/− mice exhibit higher mortality during STm infection, we found higher intestinal colonization and extraintestinal dissemination of STm in Ccl28−/− mice compared to their wild-type littermates." (PMID 39193987, 2024). "The chemokine CCL28 is highly expressed in mucosal tissues, but its role during infection is not well understood." (PMID 39193987, 2024). "(B–H) WT mice (n = 9) and Ccl28−/− mice (n = 8) were intratracheally infected with Ab and sacrificed 1 day post-infection (dpi)." (PMID 39193987, 2024). "ELISA measurements indicated enhanced expression of CCL28, IL-1β, IL-6, and TNF-α following infection with Adv-CCL28, compared with Adv-Ctl." (PMID 36713846, 2023). "The expression of the cytokines IL-18, IL-34 and chemokine CCL28 also increased following infection." (PMID 27677841, 2016). "At 4 days post-infection (dpi), CCL28 in feces was quantified by ELISA." (PMID 39193987, 2024). "Similarly, CCL28-dependent modulation of neutrophil accumulation and activation during infection can be protective or detrimental depending on the pathogen and the site of infection." (PMID 39193987, 2024). "CCL28 presented a greater concentration in the milk than did the other evaluated chemokines; however, it was the only chemokine whose concentration remained unchanged in milk during infant infection." (PMID 39867906, 2024).
infection (continued). "Therefore, CCL28 specifically promotes neutrophil accumulation in the gut during STm infection, which occurs after neutrophil production in the bone marrow and their egress into the blood circulation." (PMID 39193987, 2024). "In the attempt to verify whether a correlation does exist between augmented concentrations of mucosal IgA in HIV exposure/infection and increased quantities of CCL28, we measured CCL28, CCL25 and surface expression of CCL28 and CCL25-binding receptors in ESN, HIV-infected patients, and HC." (PMID 17912348, 2007). "Nodes 4 and 5 contain immune-related genes, including KLRD1 and NCR1, which regulate natural killer cell activity and surveillance, and CCL28 and CXCR6, which are involved in chemokine signaling and immune cell recruitment to infection sites." (PMID 41114509, 2025). "Our results indicate that CCL28 contributes to neutrophil accumulation and activation, with its receptors CCR3 and CCR10 upregulated in the mucosa during infection, where up to ~50% of neutrophils express surface CCR3." (PMID 39193987, 2024). "We found that neutrophil numbers were significantly reduced in the mucosa of infected Ccl28−/− relative to wild-type mice, identifying CCL28 as a key factor for neutrophil accumulation during infection." (PMID 39193987, 2024). "Results herewith indicate a pivotal role for CCL28 in the modulation of mucosal immunity in HIV exposure and infection and suggest a usefulness of CCL28-containing adjuvants in the development of HIV vaccines." (PMID 17912348, 2007). "Consistent with the different outcomes in the two infection models, neutrophil stimulation with CCL28 boosted the killing of Salmonella but not Acinetobacter." (PMID 39193987, 2024). "Alternatively, it is possible that infection with some, but not all, bacterial species stimulate an upregulation of CCL28 in the lactating mammary gland." (PMID 26359669, 2015). "CCL28 mediates mucosal immunity in HIV exposure and infection." (PMID 17912348, 2007). "Thus, although CCL28 modulates neutrophil accumulation in the lung during Ab infection, it fails to reduce pathogen burden in the lung likely because CCL28 stimulation does not enhance neutrophil bactericidal activity against Ab." (PMID 39193987, 2024). "Although neutrophil abundance greatly increased in the lungs during Ab infection, no other cell types profiled varied between wild-type and Ccl28−/− mice before or 1 day post-Ab infection, besides a slight deficiency in lung eosinophil levels in uninfected Ccl28−/− mice." (PMID 39193987, 2024). "Results shown here indicate that the CCL28-dependent, but not the CCL25-dependent chemotactic circuit is upregulated in HIV exposure and infection, therefore justifying the augmented mucosal concentrations of IgA seen in this condition." (PMID 17912348, 2007).
infectious disease (2 papers, 2024). A disorder directly resulting from the presence and activity of a microbial, viral, or parasitic agent in humans. "Among them, CCL28 (FC = 2.9) and Pdgfra (FC = 9.5) have important regulatory roles in triggered immune system- and infectious disease-related pathways." (PMID 38399987, 2024).
inflammation (2 papers, 2017 to 2022). Aberrant reaction of the microcirculation characterized by movement of fluid and leukocytes from the blood into extravascular tissues. "In addition, the traits of smoldering vascular inflammation were present long-term, as evidenced by the CRP and CCL28 levels." (PMID 36289630, 2022).
adenocarcinoma (1 paper, 2016). A common cancer characterized by the presence of malignant glandular cells. "There was a very significant correlation between the concentration of CCL28 and that of VEGFA in the serum of adenocarcinoma patients (Pearson correlation = 0.54, p = 0.009, R square = 0.291)." (PMID 27250766, 2016).
CCL28 also shares sentences with these, for which no sentence is quoted: oral squamous cell carcinoma (3 papers); morphine dependence (2); triple-negative breast carcinoma (2); adenolymphomas (1); allergic contact dermatitis (1); Alzheimer disease (1); Anorexia (1); atherosclerosis (1); autoimmune encephalitis (1); bacterial infection (1); benign salivary gland tumors (1); bovine tuberculosis (1); cholangitis (1); cognitive decline (1); cognitive deficits (1); dental caries (1); dependence (1); diabetic (1); gastritis (1); Glucose intolerance (1); Hepatitis (1); Hypertension (1); idiopathic pulmonary fibrosis (1); immune disorders (1); inflammatory bowel disease (1); malignant neoplasm of small intestine (1); non-small cell lung carcinoma (1); ovarian tumour (1); pancreatitis (1); peripheral vascular disease (1).
A further 12 diseases each share a sentence with CCL28 in 1 paper.